XRRA1 (X-ray radiation resistance associated 1)
Description:
May be involved in the response of cells to X-ray radiation.
Synonyms: FLJ00225
Tractability: No criterion of Open Targets' tractability assessment is met for any kind of drug.
Gene: Protein-coding gene on chromosome 11 (74,807,739 to 74,949,200, reverse strand). Ensembl gene ENSG00000166435.
Subcellular location: Cytoplasm; Nucleus
Subcellular location (Human Protein Atlas): Nucleoplasm; Nuclear bodies
Gene Ontology:
Biological process: response to X-ray
Cellular component: cytoplasm; nuclear body; nucleoplasm; nucleus
Genetic constraint (gnomAD): Loss-of-function variants: 64 observed, 75.75 expected, observed/expected ratio (o/e) 0.84, 90% interval 0.69 to 1.04. The upper end of that interval is the gene's LOEUF score, 1.04, which puts it in group 4 of 6, group 1 being the genes least tolerant of losing a copy. Missense variants: 930 observed, 945.36 expected, observed/expected ratio (o/e) 0.98, 90% interval 0.93 to 1.04. Synonymous variants: 335 observed, 373.03 expected, observed/expected ratio (o/e) 0.9, 90% interval 0.82 to 0.98.
Homologues: Orthologues: chimpanzee XRRA1 (98% identical), macaque XRRA1 (92% identical), rabbit XRRA1 (78% identical), pig XRRA1 (78% identical), dog XRRA1 (78% identical), guinea pig XRRA1 (75% identical), mouse Xrra1 (73% identical), rat Xrra1 (72% identical), tropical clawed frog xrra1 (32% identical), zebrafish xrra1 (23% identical).
Diseases named in the same sentence as XRRA1 in open-access papers:
XRRA1 is named in the same sentence as 12 diseases in open-access papers, as found by Europe PMC text mining. Sharing a sentence is not in itself a finding about the gene and the disease. The quoted sentences say what the papers report.
colorectal cancer (3 papers, 2017 to 2025). A primary or metastatic malignant neoplasm that affects the colon or rectum. "We found that blocked XRRA1 expression could lead to cell cycle G2/M arrest by the regulation of cyclin A, cyclin E, and p21 proteins in colorectal cancer (CRC) and expression of XRRA1 reduced cell cycle arrest and increased cell proliferation in CRC." (PMID 29082250, 2017).
chronic myeloid leukemia (1 paper, 2026). "In peripheral-blood proteomes, XRRA1 was quantitatively reduced in chronic myeloid leukemia yet associated with a favorable prognosis and with networks enriched for RNA regulation, apoptosis, and DNA-repair biology." (PMID 42079078, 2026). "Here, we show that XRRA1 is a stress-adaptive determinant of radioresponse identified by integrating discovery proteomics into chronic myeloid leukemia with clinical tissue validation and functional studies across multiple tumor models." (PMID 42079078, 2026).
lentivirus infection (1 paper, 2017). Virus diseases caused by the Lentivirus genus. "We inhibited XRRA1 expression by XRRA1 shRNA and also overexpressed XRRA1 by GFP-XRRA1 lentivirus infection; flow cytometric analysis was used to check changes of the cell cycle." (PMID 29082250, 2017).
cancer (4 papers, 2017 to 2026). A tumor composed of atypical neoplastic, often pleomorphic cells that invade other tissues. "To understand further the role of XRRA1 in regulating cell proliferation in cancer, we depleted XRRA1 expression by using XRRA1 shRNA, three XRRA1 shRNAs were constructed." (PMID 29082250, 2017). "In human biopsy specimens, XRRA1 protein abundance was increased in radiation-exposed tissues, and in cultured cells, ionizing radiation induced XRRA1 more strongly and persistently in normal cells than in cancer cells." (PMID 42079078, 2026). "Our results found that XRRA1 can increase cancer cell proliferation because the cell cycle was related to cell proliferation, to confirm whether the influence of cancer cells proliferation by XRRA1 was due to cell cycle regulation." (PMID 29082250, 2017). "In our study, when cancer cells were exposed to drugs and ionizing radiation, low expression of XRRA1 could increase the phosphorylation of DNA repair pathway factors CHK1, CHK2, and ATM and reduce the expression of γ-H2AX, which is believed to participate in DNA repair in the nucleus." (PMID 29082250, 2017). "Nonetheless, we find a subset of genes such as CRYBB2, RPS26, XRRA1, FAM118A,andC2ORF74, all of which show predictive gains of >50% from SNPs in multiple cancers and tumour-adjacent tissue." (PMID 40041206, 2025). "Although XRRA1 overexpression is known to be involved in cancer cell response to XR, there are no reports about whether the expression of XRRA1 in tumors can adjust radioresistance." (PMID 29082250, 2017).
tumor (4 papers, 2017 to 2026). "The X-ray radiation resistance associated 1 (XRRA1) has been suggested to regulate the response of human tumour and normal cells to X-radiation (XR)." (PMID 36293264, 2022). "X-ray radiation resistance associated 1 (XRRA1) has been found to regulate the response of human tumor and normal cells to X-radiation (XR)." (PMID 29082250, 2017). "To understand further the possible function of the XRRA1 gene, we overexpressed XRRA1 in six different tumor cell lines and found significantly increased cell proliferation compared with the control." (PMID 29082250, 2017). "Expression of XRRA1 is also closely related to the sensitivity of tumor radiotherapy." (PMID 29082250, 2017). "Therefore, we hypothesize that XRRA1 is likely to be related to tumor cell resistance to radiotherapy." (PMID 29082250, 2017).
XRRA1 also shares sentences with these, for which no sentence is quoted: breast carcinoma (1 paper); glioma (1); leprosy (1); lung carcinoma (1); melanoma (1); neuroblastoma (1); ovarian adenocarcinoma (1).